MYCN (MYCN proto-oncogene, bHLH transcription factor)
Diseases named in the same sentence as MYCN in open-access papers (continued):
Sharing a sentence is not in itself a finding about the gene and the disease.
neuroblastoma (continued). "In vitro migration assays of PBMC toward supernatants of MYCN-amplified (DZ and N91) and -nonamplified (AS and SH) neuroblastoma cell lines were performed." (PMID 36923280, 2022). "Notably, other HLA-I–low neuroendocrine cancers such as small cell lung cancer and neuroblastoma featured overexpression of the MYC family proteins MYCL and MYCN, respectively." (PMID 35775490, 2022). "Here, we observed an inverse phenomenon, with a higher functionality of DCs in contact with MYCN-nonamplified neuroblastoma." (PMID 36923280, 2022). "Here, we show for the first time that the iron chelator VLX600 inhibits mitochondrial activity and induces cell death, regardless of MYCN status in neuroblastoma cells." (PMID 35805002, 2022). "In contrast, our results indicate that in most, if not all, adrenergic neuroblastoma cells (>95% of neuroblastomas) high MYCN fails to boost cystine uptake via xc−." (PMID 35484422, 2022). "Blocking experiments demonstrate that CCL2 is responsible for these CCR2-expressing cells recruitment by MYCN-nonamplified neuroblastoma, as already observed for the migration of CCR2-expressing NKT cells toward CCL2-expressing neuroblastoma." (PMID 36923280, 2022). "The risk classification (very low risk, low risk, intermediate risk, or high risk) is based primarily on age of the patient (younger or older than 18 months), International Neuroblastoma Staging System (INSS) stage, MYCN status, ploidy of tumor cells, and Shimada histology." (PMID 35804856, 2022). "Using two neuroblastoma cells, MYCN-amplified, IMR-32 cells, and non-amplified, SK-N-AS cells, we assessed baseline levels for CCT subunits and found expressions comparable to the highly invasive triple-negative breast cancer (TNBC) cell line, MDA-MB-231." (PMID 36185250, 2022). "For neuroblastoma patients, especially those without MYCN amplification but with abnormal protein expression, MYCN IHC has great clinical value." (PMID 35820898, 2022). "In neuroblastoma cell lines, where NCYM transcript knockdown altered levels and isoforms of MYCN RNA, the transcript itself was shown to localize to the MYCN locus." (PMID 35451603, 2022). "As described already, we observed that MYCN-amplified neuroblastoma cells lines (DZ and N91) lacked expression of HLA class I molecules, whereas AS and SH expressed it at high level." (PMID 36923280, 2022). "A general picture of the tumor microenvironment in neuroblastoma is the differences in the cellular landscape of MYCN-amplified vs MYCN non-amplified neuroblastomas." (PMID 35362827, 2022). "In the current study, the recruitment and the migration of immune cells induced by neuroblastoma cell lines with MYCN amplification or not were analyzed." (PMID 36923280, 2022). "MYCN suppression was varied in a neuroblastoma cell line that expresses myc-N, so the regulation of MYC and the cellular response to BET inhibition differ between hematologic and solid tumor types, such as neuroblastoma." (PMID 36286044, 2022). "Interestingly, neuroblastoma initiation in TH-MYCN mouse models involves sustained EZH2 expression and the suppression of PRC2 targets in MYCN-expressing sympathetic neuroblasts." (PMID 35681734, 2022). "In neuroblastoma, ASCL1 has been described as part of a core regulatory circuit of developmental regulators whose high expression is maintained by mutual cross-activation of a network of super enhancers and is further augmented by the activity of MYC/MYCN." (PMID 36263020, 2022). "In comparison to the prognostic value of MYCN, one of the main prognostic indicators in neuroblastoma, negative PSA-NCAM and NCAM expression were even stronger predictors of unfavorable outcomes." (PMID 35574403, 2022). "Patient G-03 was initially diagnosed with localized neuroblastoma (stage 2/3) at one month and was negative for MYCN amplification." (PMID 36497290, 2022).
neuroblastoma (continued). "E2F3 was also a prognostic maker of neuroblastoma independent of MYCN amplification, age of diagnosis and E2F1 expression in E-MTAB-1781 datasets." (PMID 35764946, 2022). "At diagnosis, patients with MYCN-non-amplified (MYCN-NA) neuroblastoma received no cytotoxic chemotherapy (n=4) or intermediate-risk chemotherapy (n=11)." (PMID 36686814, 2022). "Altogether, these results demonstrate the major involvement of the CCR2/CCL2 axis in the recruitment of APC by MYCN-nonamplified neuroblastoma." (PMID 36923280, 2022). "MYCMI-7 inhibited cell growth in a MYC-dependent manner, as demonstrated by MYC knockout versus reconstituted Rat1 cells and neuroblastoma cells with or without MYCN amplification." (PMID 36874405, 2022). "FOXM1 is a major driver of embryonic stem cell regulatory programs in neuroblastoma patients with MYCN amplified tumors and stage 4 non-amplified tumors, and expression correlates with poor patient outcome and therapy resistance." (PMID 35428820, 2022). "This may be why verlindamycin proved to be so efficient in neuroblastoma—it is a single molecule able to inhibit LSD1 and downregulate MYCN." (PMID 34522028, 2022). "Since most MYCN-nonamplified neuroblastoma cells exhibited high MYC levels, we also inhibited EZH2 expression in SK-N-AS, SH-SY5Y, and SK-N-SH cells." (PMID 35013218, 2022). "Longer treatments over 24 h showed a consistent response to VLX600 in both MYCN-amplified and non-amplified cells, suggesting that autophagy is not properly induced in neuroblastoma cells exposed to VLX600." (PMID 35805002, 2022). "Poorly differentiated neuroblastoma without MYCN amplification was diagnosed from a biopsy specimen." (PMID 35883927, 2022). "The same dataset was analyzed according to the high-risk Neuroblastoma Study 1.7 of SIOPEurope (SIOPEN) stratification risk, where HR-NB is defined as stages 2, 3, 4, and 4S with MYCN-amplification and stage 4 MYCN non-amplified > 12 months at diagnosis." (PMID 35715791, 2022). "As opposed to MYCN-amplified cell lines, MYCN-nonamplified neuroblastoma was highly chemoattractive for monocytes, MDC and PDC." (PMID 36923280, 2022). "Conversely, reduced T-cell infiltration has been observed in primary neuroblastoma tumors with MYCN amplification, together with lower IFN pathway activity and chemokine expression, suggesting that MYCN amplification could impact immune cell recruitment." (PMID 36923280, 2022). "E2F1 and E2F3 were prognostic factors in neuroblastoma, independent of MYCN amplification and age of diagnosis." (PMID 35764946, 2022). "We also looked at immunomodulation induced by neuroblastoma cell lines, and found that tumors without MYCN amplification create a microenvironment that favors the activation of DC." (PMID 36923280, 2022). "In accordance, MILIP was expressed at higher levels in MYCN-amplified than MYCN-nonamplified neuroblastomas." (PMID 36445966, 2022). "Aberrant amplification and/or overexpression of MYCN is not only observed in NEPC, but also in other aggressive tumors, such as neuroblastoma, medulloblastoma, retinoblastoma, small cell carcinoma of the lung, pancreatic neuroendocrine tumors, and glioblastoma to name a few." (PMID 35883689, 2022). "In order to explore de novo mutations occurring during development of ALK inhibitor resistance, we cultivated NBLW-R neuroblastoma cells (ALKF1174L, MYCN-amplified) with increasing concentrations of lorlatinib or ceritinib for a period of 3 months to generate resistant cell lines." (PMID 35689207, 2022). "Therefore, we tested how specific MYCN inhibition by BGA002 and RA treatment affected CRABP1/2 expression in neuroblastoma cell lines." (PMID 35490242, 2022). "In this paper, we highlighted that E2F1 and E2F3 were prognostic makers of neuroblastoma independent of MYCN amplification and age of diagnosis." (PMID 35764946, 2022).
neuroblastoma (continued). "MYCN mRNA-containing microvesicles were detectable in three distinct MYCN-amplified neuroblastoma cell lines but absent in three neuroblastoma cells with MYCN-non-amplification." (PMID 35681607, 2022). "In addition, MYCN overexpression induces E2F5 expression and promotes cell proliferation in neuroblastoma." (PMID 36479072, 2022). "The protooncoprotein N-Myc, which is overexpressed in approximately 25% of neuroblastomas as the consequence of MYCN gene amplification, has long been postulated to regulate DNA double-strand break (DSB) repair in neuroblastoma cells, but experimental evidence of this function is presently scant." (PMID 36445966, 2022). "Compared to chromaffin cells, the cultured sympathetic neuroblasts showed a significantly higher sensitivity to THZ1 with an EC50 of about 30 nM, which is between the sensitivity of the neuroblastoma cell lines with and without MYCN amplification." (PMID 35681734, 2022). "To identify the chemokines responsible for the strong attraction of monocytes and DC by MYCN-nonamplified neuroblastoma, we looked for the presence of 38 chemokines." (PMID 36923280, 2022). "This lack of antigen presentation in MYCN-amplified neuroblastomas is responsible for the escape from cytotoxic T cell and interferon-mediated immune responses." (PMID 35362827, 2022). "Pediatric neuroblastoma patients without MYCN amplification and with lower E2F1 expression levels had significantly longer event free survival and overall survival in GSE16476, GSE85047 and E-MTAB-1781 datasets." (PMID 35764946, 2022). "Several mTOR inhibitors have already been approved for the therapeutic treatments of different types of cancer, while in neuroblastoma new clinical trials are ongoing (NCT02337309, NCT03213678) making mTOR inhibition a very promising therapeutic avenue for MYCN-deregulated childhood cancers." (PMID 36139583, 2022). "We also looked at immunomodulation induced by neuroblastoma cell lines, and found MYCN-nonamplified neuroblastoma cell lines were able to create a microenvironment where DC activation is enhanced." (PMID 36923280, 2022). "In line with our previous studies, we defined neuroblastomas as telomerase positive if TERT expression was above the threshold, if they harbored a TERT RA, or if they were MYCN amplified, as the latter had been shown to directly upregulate TERT expression in neuroblastoma." (PMID 36153564, 2022). "We used the neuroblastoma cell lines SH-SY5Y (ALKF1174L) and LAN-5 (ALKR1275Q, MYCN-amplified), to represent ALK-mutated neuroblastoma within a genomic background either with or without MYCN amplification." (PMID 35689207, 2022). "Together, these findings suggest that the MYCN-ATF4 axis, in cooperation with epigenetic regulators, including KDM4C, is a major mechanism to increase the pools of amino acids for sustaining the MYCN-mediated growth program in neuroblastoma." (PMID 36077650, 2022). "Others have used DNA alkylation to target MYCN gene amplification to reduce the number of MYCN copies, which resulted in decreased neuroblastoma proliferation in MYCN amplified, but not MYCN non-amplified, cells." (PMID 35454859, 2022). "The mRNA expression levels of CCNE1, CDK2, CHEK2 and SESN1 in paediatric neuroblastoma patients with or without MYCN amplification were also investigated." (PMID 35655142, 2022). "Unexpectedly, the IC50 value of MYCN non-amplified and MYCN-amplified neuroblastoma cells were relatively comparable." (PMID 35805002, 2022). "While all cell lines were negative for MYCN amplification (two copies of gene in the genome), HTR3A protein expression was associated with expression of major drivers of aggressive neuroblastomas, N-MYC and c-MYC44,45, or one of the core stemness factors SOX2." (PMID 35614045, 2022).
neuroblastoma (continued). "Applying specific thermal doses via PBNP-PTT offers a potential strategy for recovering immune surveillance of both MYCN-non-amplified and, to a lower extent, MYCN-amplified neuroblastoma by upregulating HLA-ABC and/or HLA-DR." (PMID 35326601, 2022). "Here, our results suggest that mitochondria inhibitor VLX600 promotes sensitization of neuroblastoma cells in nutrition-restricted conditions (spheroids condition, insufficient autophagy and glucose deprivation) regardless of MYCN expression." (PMID 35805002, 2022). "Only one case, with resection at 48 weeks due to mass persistence, proved to be MYCN amplified neuroblastoma and of note the plasma evaluated at diagnosis did not confirm MYCN amplification." (PMID 36011005, 2022). "Other investigators propose that since MYCN and CIP2A are expressed during embryologic formation of the central nervous system, these two oncogenic proteins could be working together in neuroblastoma tumorigenesis." (PMID 35454859, 2022). "It is worth noting that in neuroblastoma, TWIST1 is a direct transcriptional target of MYC/MYCN." (PMID 34716856, 2022). "Using functional MYCN synthetic lethal metabolic and genetic screens, we further identified cyst(e)ine deprivation and glutathione peroxidase 4 (GPX4) inhibition as selective liabilities in MYCN-amplified neuroblastomas." (PMID 35484422, 2022). "Indeed, in neuroblastoma and in other models, ALK activation has been shown to cooperate with MYCN but also regulate MYCC expression." (PMID 36337169, 2022). "Reduction of MAX was observed in some additional neuroblastoma cell lines, apparently irrespective of MYCN amplification status." (PMID 36874405, 2022). "Amplification of this oncogene is the most important negative prognostic indicator in neuroblastoma, and MYCN amplification automatically confers the patient into the high-risk treatment group." (PMID 35454859, 2022). "By analyzing publicly available, large neuroblastoma patient cohorts, we presented DHODH expression as an independent prognostic marker in neuroblastoma after adjusting for known adverse factors, such as disease stage, age, and MYCN amplification." (PMID 35943801, 2022). "Pediatric neuroblastoma patients without MYCN amplification and with lower E2F3 expression levels had significantly longer event free survival and overall survival in GSE16476, GSE85047 and E-MTAB-1781 datasets." (PMID 35764946, 2022). "Although MYCN amplification has been unequivocally characterized as unfavorable in neuroblastomas, to date, there are no directly druggable targets, which remains a particular clinical dilemma." (PMID 34069817, 2021). "Combined treatment with another BRD4 inhibitor, I-BET151, and alisertib is efficacious in exerting antitumor effects against neuroblastoma with or without MYCN amplification both in vitro and in vivo." (PMID 33451333, 2021). "Our results highlight the potential of fatty acid synthesis inhibition as a therapeutic approach for neuroblastoma irrespective of MYCN-status." (PMID 33659885, 2021). "MYCN deregulation is a recognized driver for numerous childhood and adulthood neuronal and nonneuronal tumors including neuroblastoma, medulloblastomas, rhabdomyosarcoma, neuro-endocrine prostate cancer, Wilms tumor, lymphoma and AML." (PMID 34508175, 2021). "MYCN non-amplified younger patients with higher DST expression levels had the best clinical overall survival in neuroblastoma." (PMID 34116676, 2021). "CHK1 is highly expressed in MNA compared to MYCN non-amplified (non-MNA) and in high-risk compared to low risk non-MNA neuroblastoma patients." (PMID 34508175, 2021). "The cell line panel covers the full spectrum of neuroblastoma’s MYCN genetic backgrounds, ranging from non-amplified to MYCN amplified cells and from almost undetectable expression of MYCN to highly expressing cells." (PMID 33968920, 2021).
neuroblastoma (continued). "Fourteen different diagnoses, including sub-categories of neuroblastoma (NB; MYCN amplified and not amplified) and rhabdomyosarcoma (RMS; fusion positive and negative) were represented." (PMID 34818552, 2021). "We demonstrated in our study cohort that the ODC SNP has prognostic significance in MYCN amplified and non-amplified neuroblastoma with the AA genotype indicative of a better prognosis." (PMID 33918978, 2021). "The present study suggested the relative heterogeneity of MYCN non-amplified pediatric neuroblastoma." (PMID 34116676, 2021). "Recently, two clinical trials have revealed that 60 mg/m2 alisertib per dose for 7 days is tolerable with a standard irinotecan and temozolomide backbone and shows antitumor activity, particularly in neuroblastoma patients with MYCN-nonamplified tumors." (PMID 33451333, 2021). "Notably, we found that RORα expression predicts outcome independently of current prognostic factors, including age at diagnosis, International Neuroblastoma Staging System (INSS) stage, and MYCN status." (PMID 34183658, 2021). "Although MYCN-amplification strongly correlates to poor clinical outcome in neuroblastoma patients, there are no MYC-targeted therapies available in the clinic to date." (PMID 33659885, 2021). "ALCAM, CACNA2D3, DST, EPB41L4A and KIF1B were highly expressed in MYCN non-amplified younger neuroblastoma patients." (PMID 34116676, 2021). "Further, DNA binding motif analysis suggested a role as a core regulatory circuit member in MYCN-driven neuroblastoma, but so far, ChIP-seq data were not available to support this." (PMID 34638267, 2021). "To further examine ALYREF as a transcriptional coactivator for MYCN, we evaluated the effect of ALYREF knockdown on USP3 gene transcription in SHEPMYCN3 neuroblastoma cells, which express MYCN under the control of doxycycline, therefore minimising ALYREF knockdown effects on MYCN stability." (PMID 33767157, 2021). "MYCN non-amplified neuroblastoma patients with lower expression levels of ALCAM, CACNA2D3, DST, EPB41L4A or KIF1B were with lower overall survival in TARGET dataset, GSE49710 dataset and GSE85047 dataset." (PMID 34116676, 2021). "On the other hand, MYCN-amplified neuroblastoma cells exhibit higher GLS2 expression levels (compared to cells with nonamplified MYCN) and are particularly prone to apoptosis upon glutamine deprivation." (PMID 33746066, 2021). "However, the co-upregulation of both, MYCN protein and the miR-17-92 cluster miRNAs, in MNA neuroblastoma suggests that miRNA-dependent regulation of MYCN expression is substantially modulated by trans-acting factors controlling MYCN expression via the 3’UTR." (PMID 34026620, 2021). "In addition, PNUTS knockdown resulted in decreased N-Myc protein, and repressed the progression of MYCN-amplified neuroblastoma." (PMID 34658888, 2021). "Using heatmaps, we showed that those genes were all over-expressed in MYCN non-amplified younger neuroblastoma patients." (PMID 34116676, 2021). "Age alone was an independent prognostic marker of MYCN non-amplified neuroblastoma in GSE49710 and GSE85047 datasets, but not in TARGET dataset." (PMID 34116676, 2021). "Compared with MYCN non-amplified older neuroblastoma patients, MYCN non-amplified younger neuroblastoma patients had better clinical outcomes." (PMID 34116676, 2021). "Overall, iron chelators treatment by the novel thiosemicarbazone DpC induces potent cell death of neuroblastoma cells, while targeting some of the major drivers of aggressive neuroblastomas, regardless of their MYCN status." (PMID 35008802, 2021).